GRIN2A (glutamate ionotropic receptor NMDA type subunit 2A)
Diseases named in the same sentence as GRIN2A in open-access papers (continued):
Sharing a sentence is not in itself a finding about the gene and the disease.
epilepsy (continued). "Alterations of the N-methyl-d-aspartate receptor (NMDAR) subunit GluN2A, encoded by GRIN2A, have been associated with a spectrum of neurodevelopmental disorders with prominent speech-related features, and epilepsy." (PMID 30544257, 2019). "Four studies have reported 34 patients with GRIN2A mutations who were diagnosed with ESESS/CSWSS/epilepsy-aphasia spectrum." (PMID 29976148, 2018). "We identified one de novo missense GRIN2A mutation (Asp731Asn, GluN2A(D731N)) in a child with unexplained epilepsy and DD." (PMID 28182669, 2017). "N-methyl-D-aspartate receptors (NMDAR) subunit GRIN2A/GluN2A mutations have been identified in patients with various neurological diseases, such as epilepsy and intellectual disability / developmental delay (ID/DD)." (PMID 28182669, 2017). "In this study, next generation sequencing identified a GRIN2A missense mutation c.2191G>A (p.Asp731Asn, hereafter referred to as GluN2A-D731N) from a pediatric patient diagnosed with epilepsy and DD." (PMID 28182669, 2017). "Polymorphisms in the GRIN2A gene are associated with epilepsy and different neurological and mental disorders." (PMID 28396702, 2017). "Mutations in the N-methyl-D-aspartate receptor (NMDAR) gene GRIN2A cause epilepsy-aphasia syndrome (EAS), a spectrum of epileptic, cognitive and language disorders." (PMID 28242877, 2017). "Genetic variants in the GluN2B gene, GRIN2B, have been implicated in sporadic ASD, while mutations of GRIN2B and GRIN2A (the GluN2A gene) have been associated with epilepsy and intellectual disability." (PMID 27134685, 2016). "GRIN2A/GluN2A subunit constitutes a locus for mutations in a subset of patients with early-onset epilepsy." (PMID 26933583, 2015). "In more than 80% of patients, GRIN2A variants cause epilepsy and speech disorders." (PMID 40149474, 2025). "The effectiveness of memantine on drug‐resistant early‐onset epilepsy in individuals with gain‐of‐function GRIN2 variants (GRIN2A, GRIN2B and GRIN2D) is mixed, and previously, memantine treatment did not improve seizure frequency in four patients with GRIN2B gain‐of‐function mutations." (PMID 40827489, 2025). "However, single epilepsy risk genes such as the ionotropic glutamate receptor GRIN2A (avg log2FC = 2.25 corP < .003), Doublecortin (DCX, avg." (PMID 40704780, 2025). "Moreover, mutations in the Grin2a gene are also linked to epileptic encephalopathy, a severe form of epilepsy that presents with early onset, frequent seizures, and significant developmental and cognitive impairments." (PMID 39452036, 2024). "In addition, it is worth noting that GRIN2A variants exhibit a strong correlation with epilepsy‐aphasia syndromes, a group of age‐dependent epileptic, cognitive, and language disorders with a characteristic electroencephalographic pattern." (PMID 39474911, 2024). "Also, we reviewed previously published papers about missense GRIN2A variants in epilepsy to learn more about the correlations between subregional effects, functional changes, and phenotypic diversity." (PMID 39474911, 2024). "Also, we reviewed previously published papers about GRIN2A variants in epilepsy to learn more about the correlations between their locations, functional changes, and clinical manifestations." (PMID 39474911, 2024). "Different epilepsy syndromes including Landau-Kleffner syndrome, epileptic encephalopathy, childhood epilepsy, autosomal dominant rolandic epilepsy and infantile-onset epileptic encephalopathy have been linked to GRIN2A mutations." (PMID 37319252, 2023). "Genetic mutations in GRIN2A are associated with epilepsy-aphasia spectrum disorders." (PMID 37016703, 2023). "Also, mutations of the GRIN2A gene have been identified in epilepsy with electrical status epilepticus of slow-wave sleep, epilepsy syndromes associated with ESES syndrome, Landau–Kleffner syndrome, and in autosomal-dominant Rolandic epilepsy." (PMID 38069426, 2023).
epilepsy (continued). "In summary, severe loss- and gain-of-function GRIN2A mutations associated with epilepsy-aphasia spectrum disorders lead to similar dysfunctional NMDAR-mediated synaptic currents in CA1 pyramidal neurons when expressed in cultured mouse hippocampal slices, albeit via different mechanisms." (PMID 35228668, 2022). "Previous studies reported that epilepsy related GRIN2A missense mutations were reviewed." (PMID 34720871, 2021). "So far, more than 80 GRIN2A gene variants have been found in epilepsies, especially in EAS." (PMID 33240831, 2020). "Therefore, NMDA receptor can stand as a target for development of drug since GRIN2A mutations were reported in many patients with ESESS/CSWSS/epilepsy-aphasia spectrum (N = 38)." (PMID 29976148, 2018). "Several case-control studies have identified mutations in the GRIN2A gene in patients with different forms of epilepsy, including early-onset epileptic encephalopathy, continuous spike-and-waves during slow-wave sleep syndrome (CSWSS), Landau-Kleffner syndrome (LKS), and Rolandic epilepsy." (PMID 28182669, 2017). "Therefore, LOF of GRIN2A was potentially pathogenic for epilepsy." (PMID 34720871, 2021). "Defects in GRIN2A are related to many neurological disorders, including developmental delay, evolving to intellectual disability (DD/ID), epilepsy, speech and language disorders, movement disorders, and neuropsychiatric disorders." (PMID 39519164, 2024). "GRIN2A‐related epilepsy encompasses not only the well‐known epilepsy‐aphasia syndrome but also some developmental and epileptic encephalopathies, even IGE." (PMID 39474911, 2024). "We show that the DD/ID-linked M653I and S809R, epilepsy-linked A727T and SCZ-linked Y698C GRIN2A variants all result in LoF, but, when co-expressed with wild-type GRIN2A, only M653I and S809R exert a dominant negative effect." (PMID 38307912, 2024). "Mutations in specific genes such as GABRA1, GRIN2A, and CACNG2 have been associated with different types of epilepsy, providing valuable models for understanding how these genetic alterations affect neuronal function and trigger epileptic seizures." (PMID 39452036, 2024). "Similar findings have been reported regarding seizure types in epilepsy patients, where epileptic spasms are exclusively observed in individuals with missense variants in the TMD + Linker regions of GRIN2A subunits." (PMID 39596430, 2024). "In 8 patients, one or more epilepsy genes, GRIN2A, TET3, SCN1A, SCN8A, ADGRV1, DLG4, and SLC12A5, were found, and 12 patients had no genetic mutations." (PMID 38813507, 2023). "In various neuropsychiatric disorders, over 70% of the individuals with GRIN2A variants are diagnosed with epilepsy, whereas less than 30% of the individuals with GRIN2B variants have epilepsy." (PMID 35680847, 2022). "The first group is the studies that described the generation of patient-specific iPSC lines that carry genetic variants in genes associated with epilepsy, such as SCN1A, GNB5, LGI1, GRIN2A, KCNC1, or KCNA2." (PMID 36552721, 2022). "There were defects of GRIN2A related to epileptiform discharges and transient microstructural brain abnormalities in mice with epilepsy." (PMID 35069111, 2021). "Both had mild epilepsy during childhood that resolved similar to that previously seen in GRIN2A cases (# 245570; FESD)." (PMID 33710394, 2021).
epilepsy (continued). "Looking into the DEG subnetwork, we found that some well-known ASD candidate genes, such as Kcnma1, Shank2, Cacna1a and Cacna1b, and epilepsy candidate genes, such as Scn3a, Grin2a, Gabrg2, and Grin2b, are hub genes in this subnetwork." (PMID 32033586, 2020). "Genes most frequently shared among class 1 modules (such as DLG4, GRIN2A, PRKCB, and SNAP25) have been associated with epilepsy, synaptic function, and neuronal processes." (PMID 31653223, 2019). "GRIN2A codes for the NR2A subunit of NMDA receptors, and gain-of-function mutations lead to epilepsy with marked language difficulties." (PMID 28954894, 2018). "The two modules had the proteins, such as KCNA2, GABRA1, and GRIN2A, which had been recently be discovered as novel epilepsy genes." (PMID 28388656, 2017). "The epilepsy risk gene GRIN2A was not rescued and remained upregulated (avg log2FC = 2.664, corP < 2.36E4)." (PMID 40704780, 2025). "Besides AD, GRIN2A and GRIN2D are NMDARs, whose associated encephalopathies range from intellectual disability to epilepsy-aphasia spectrum phenotypes." (PMID 40727427, 2025). "The prevalence of GRIN2A-related speech disorders and epilepsy in the general population is unknown; however, estimates can be made for some of the classic disorders." (PMID 40727434, 2025). "According to Samanta, the discovery of GRIN2A as the main monogenic etiology of the epilepsy–aphasia spectrum led to a hypothesis on the possibility of precision therapies." (PMID 38397281, 2024). "Notably, 22 out of the 45 reported (candidate) genes are known to be related to a broader phenotype than DLD, including intellectual disability, epilepsy, and/or autism (e.g., GRIN2A, CNTNAP2, CNTNAP5, AUTS2)." (PMID 38298611, 2024). "Genetic tests were performed in 24 patients, none of them harbored known pathogenic epilepsy genes, including GRIN2A." (PMID 39184857, 2024). "We then tested whether either SCZ-linked or epilepsy and DD/ID-linked variants would exert a dominant-negative effect on NMDAR function when co-expressed with an equal amount of wild-type GRIN2A (as well as the obligate GRIN1 subunit)." (PMID 38307912, 2024). "Yet again, as for CNTNAP2, FOXP1 and TBR1, pathogenic variants in GRIN2A have not been identified in cohorts ascertained for a primary diagnosis of speech or language disorder in the absence of epilepsy." (PMID 38366112, 2024). "Here, we present electrophysiological data for a representative set of GRIN2A variants associated with SCZ, epilepsy or DD/ID, and propose a pathomechanistic model that could potentially aid in predicting phenotype severity of GRIN2A variants." (PMID 38307912, 2024). "Approximately 78% of patients with GluN2A/Grin2a mutations have epilepsy, and the underlying mechanism of this association is not well characterized." (PMID 36937661, 2023). "Here, we demonstrate generation of an animal model of an individual epilepsy patient with an ultra-rare variant of the NMDA receptor subunit GRIN2A, without the need for germline transmission and breeding." (PMID 38106154, 2023). "GRIN2A-related speech disorders and epilepsy affects individuals from a young age." (PMID 37319252, 2023). "Related studies have shown that GRIN1, GRIN2A, and GRIN2B mutations can lead to epilepsy." (PMID 35069111, 2021). "A rare variant of GRIN2A associated with epilepsy disrupts CaMKIIα phosphorylation of GluN2A and NMDAR trafficking, which demonstrates a role of GluN2A for CaMKIIα phosphorylation in receptor targeting and suggests that the defects of NMDAR trafficking are related to epilepsy." (PMID 35069111, 2021).
epilepsy (continued). "Consistent with the converged network module of the PPI subnetworks for autism, epilepsy, and learning/memory, the shared module of these three gene-pathway bipartite subnetworks also involve NMDARs (Grin1, Grin2a, and Grin2b) as hubs connecting to 16 pathways." (PMID 32033586, 2020). "A study by our group that included 20 epilepsy patients with personal or family history of heart rhythm disturbance/cardiac arrhythmia/sudden death identified four missense variants in epilepsy genes CDKL5, CNTNAP2, GRIN2A, and ADGRV1, with complete segregation within the family." (PMID 31018519, 2019). "Our comprehensive analysis shows that the GRIN2A-related phenotypic spectrum does not only comprise well established epilepsy-aphasia disorders, but is much broader and ranges from normal or near-normal development to non-specific developmental and epileptic encephalopathy." (PMID 30544257, 2019). "Five patients with RE carried a rare CNV that disrupted genes associated with other epilepsies (KCTD7, ARHGEF15, CACNA2D1, GRIN2A and ARHGEF4), and 17 cases carried CNVs that disrupted genes associated with other neurological conditions or that are involved in neuronal signalling/development." (PMID 29789371, 2018). "In the siblings, the younger brother showed a novel GRIN2A variant (c.3175 T > A), while the older one carried the same GRIN2A variant, associated with two likely pathogenetic variants in SCNIB (c.632 > A) and KCNQ2 (1870 G > A) genes, which have been implicated in childhood epilepsies." (PMID 37679850, 2023). "Although Grin2c gene has not been related to epileptogenic processes, the subunit GRIN2A appears to be associated with the broadest and best characterized phenotypic spectrum, including a variety of disorders of the epilepsy aphasia spectrum and developmental and epileptic encephalopathy." (PMID 32528245, 2020). "Among these, GRIN2A, GABRB3, and GRIN2D have been reported previously, supporting their roles in epilepsy pathophysiology." (PMID 40313715, 2025). "CSWS has been described in various genetic conditions, including common epilepsy-related ion channel genes like SCN2A or KCNQ2, as well as the N-methyl D-aspartate receptor subunit gene GRIN2A, that show overlapping expression at neuronal synapses." (PMID 33126500, 2020). "Recently, some studies showed that children with EAS share some common epilepsy genes, including GRIN2A (glutamate receptor, ionotropic, N-methyl d-aspartate 2A), which is the most advocated one." (PMID 33240831, 2020). "GluN2A/GRIN2A is one of the subunits of NMDAR and plays an important role in epilepsy." (PMID 36937661, 2023). "Genes encoding NMDAR subunits (such as GRIN1, GRIN2A, and GRIN2B) have been identified to be associated with broad-spectrum phenotypes, including epilepsies, epilepsies with NDD, and NDD without seizures." (PMID 38249294, 2023). "It is possible that the GRIN2A variants with the mild impact played a risk, rather than a causal role in IGE, and were associated with only increased susceptibility to epilepsy." (PMID 34720871, 2021). "Lastly, we identified six individuals with oligosymptomatic GRIN2Anull-related phenotypes, i.e. isolated non-syndromic mental disorder without other GRIN2A-specific features, such as ID (absent in 6/6) or epilepsy (absent in 2/6, both of which are adult carriers)." (PMID 41087560, 2026). "We additionally show that M653I and S809R, LoF GRIN2A variants associated with DD/ID, exert a dominant-negative effect when co-expressed with a wild-type GluN2A, whereas E58Ter and Y698C, SCZ-linked LoF variants, and A727T, an epilepsy-linked LoF variant, do not." (PMID 38307912, 2024). "However, different from those in epilepsy, GRIN2B but not GRIN2A variants are mostly associated with ID." (PMID 35680847, 2022).
epilepsy (continued). "For some genes, such as GRIN2A, which codes for severe forms of idiopathic focal epilepsy, and PCDH19, which has similarities to Dravet syndrome, the therapeutic concepts of these forms of epilepsy may also apply to these genes." (PMID 33519703, 2020).
Cognitive impairment (49 papers, 2014 to 2026). Abnormal cognition is characterized by deficits in thinking, reasoning, or remembering. "Most of the drugs corresponding to GRIN2A are antidepressants as well as antipsychotics, such as apimostinel, esketamine, and haloperidol, which improve cognitive deficits caused by the early stages of Alzheimer’s disease." (PMID 39650656, 2024). "In all mutations, GRIN2A variants are associated with neurological diseases including developmental and epileptic encephalopathy, which may be manifested as seizures, mild speech and language delay, and cognitive impairment." (PMID 35069111, 2021). "Knockdown of astrocytic GRIN2A aggravates Aβ‐induced memory and cognitive deficits by regulating NGFs." (PMID 41414708, 2025). "In fact, previous studies have demonstrated that GRIN2A knockdown accelerates memory and cognitive deficits in mice." (PMID 38672412, 2024). "Functional validation and prediction targets for miR-137 include multiple risk genes for cognitive impairment in SCZ, such as CACNA1C, GABRA1, GRIN2A, and HTR2C." (PMID 36406755, 2022). "The genes of cognitive impairment regulated by non-coding RNAs include GRIN2A, BDNF, HTR2A, and NMDAR." (PMID 36406755, 2022). "What is more, shGrin2a + Aβ rats showed a significant reduction of preference index (preference index: shGrin2a + Aβ: 0.01 ± 0.01 versus Aβ: 0.09 ± 0.04, p < 0.05), which indicates astrocyte‐specific Grin2a knockdown deteriorates Aβ‐induced cognitive deficit." (PMID 34291567, 2021). "The results showed astrocytic Grin2a knockdown aggravated Aβ‐induced memory and cognitive deficits through modulating the synthesis, mature and secretion of NGF." (PMID 34291567, 2021). "Moreover, in the rat model, Grin2a is a synaptic protective factor in astrocytes early in Aβ exposure, and knockdown of Grin2a exacerbates β-amyloid-induced memory and cognitive deficits." (PMID 39650656, 2024). "A broad array of synaptic markers, including GRIN2A and GRIN2B, is often downregulated in prefrontal cortex in advanced age and in AD, with loss of components of the excitatory synapse, thereby potentially contributing to the modest cognitive deficits seen here in old animals." (PMID 35798912, 2022).